DHODH (dihydroorotate dehydrogenase (quinone))
Diseases named in the same sentence as DHODH in open-access papers (continued):
Sharing a sentence is not in itself a finding about the gene and the disease.
cancer (continued). "Meanwhile, combination of DHODH inhibitors with other anti-cancer drugs is a promising approach to achieving clinical benefits in various tumor therapies as DHODH inhibitors alone have limited therapeutic windows and may not achieve desired outcomes." (PMID 33971967, 2021). "Some of the genes specifically mutated in noncoding regions were identified as highly potent cancer drivers, of which BAD had a mutation hotspot in the 3’UTR, DHODH had a mutation hotspot in the Kozak sequence in the 5’UTR, and CHCHD2 frequently showed mutations in the 5’UTR." (PMID 34900699, 2021). "Besides traditional cell toxicity of anti-cancer drugs, DHODH inhibitors in combination with novel targeted anti-cancer drugs attracted much attention." (PMID 33971967, 2021). "Although DHODH is not known to be mutated or over-expressed in patients with cancer, DHODH inhibitors are able to shrink tumor burden and improve survival by inducting leukemic cells differentiation in preclinical AML models." (PMID 34858835, 2021). "Several studies in solid tumors have previously shown that DHODH inhibition could sensitize cancer cells to chemotherapy, eventually overcoming chemoresistance, so we started our search for synergy with Ara-C, decitabine and idarubicin." (PMID 33670894, 2021). "Leflunomide, as a potential anti-cancer drug, is considered primarily as an inhibitor of DHODH." (PMID 34577124, 2021). "Promisingly, this study indicated that DHODH inhibitors treatment either alone in GPX4low cancers, or in combination with ferroptosis inducers in GPX4high cancer could confer tumor inhibition." (PMID 34611144, 2021). "DHODH suppression has been reported to confer a metabolic vulnerability in KRAS-driven cancers." (PMID 32824193, 2020). "This may open up the possibility for uncovering new mechanisms by which cancer stem cells may be targeted through the inhibition of DHODH or nucleoside transport." (PMID 32900849, 2020). "Future studies should be aimed at investigating whether a decreased nucleotide pool or decreased ROS levels may account for the anticancer activity of DHODH inhibitors, as well as the role of DHODH-produced ROS in cancer development." (PMID 31819197, 2020). "In addition, several interesting individual genes have also emerged, such as DHODH, the highest scoring cancer-specific essential gene and MDM2, which is one of the highest scoring ESC-specific essential genes." (PMID 31889988, 2019). "As a downstream effector, DHODH would be a promising target whose inhibition could be an effective anti-cancer strategy." (PMID 31551419, 2019). "However, knockdown of CAD or GOT1 strongly, while DHODH knockdown marginally, sensitized cancer cells to hypoxia." (PMID 30643150, 2019). "These evidences indicated that DHODH might be a potential target for drug intervention in cancer treatment." (PMID 29348830, 2017). "The cytotoxic effect that was observed in transformed mouse embryonic fibroblasts raised the question as to whether the combination of DHODH and Chk1 inhibitors would also be effective in a model of human cancer cells." (PMID 29221122, 2017). "Recently, DHODH was reported to play essential roles during tumorigenesis and cancer development." (PMID 29348830, 2017).
cancer (continued). "Importantly a similar significant increase in cell death was observed upon dual siRNA mediated depletion of Chk1 and DHODH in both murine and human cancer cell models." (PMID 29221122, 2017). "Elevated DHODH expression and increased activity have been observed in multiple types of cancers." (PMID 25621173, 2015). "An experimental analysis of a group of cancer cell lines with low and high GPX4 expression demonstrated that inhibiting DHODH could induce ferroptosis in tumor cells with low GPX4 expression while enhancing ferroptosis resistance in cancer cells with high GPX4 expression." (PMID 40740786, 2025). "Therefore, using DHODH inhibitors could potentially offer a dual benefit: treating cancer or rheumatoid diseases while minimally compromising HF management." (PMID 39737072, 2024). "However, the role of DHODH in cancer cell DNA replication and its impact on modulating a treatment response is currently unknown." (PMID 38136273, 2023). "Importantly, however, brequinar was recently shown to act synergistically with the FDA-approved drug SAS to suppress tumor growth by potently inducing ferroptosis, suggesting that DHODH may indeed serve as a viable target for treating cancer." (PMID 37735472, 2023). "However, little is known about whether brequinar could kill cancer cells by increasing DHODH-mediated ferroptosis." (PMID 36672495, 2023). "Therefore, DHODH may be a combinative therapeutic target that induces ferroptosis-mediated cell death in GPX4low cancers." (PMID 37580393, 2023). "Moreover, whether inhibition of DHODH could exert a synergistic function with cisplatin for treating human cancers remains undefined." (PMID 36672495, 2023). "DHODH overexpression in tumors can lead to resistance to chemotherapy, so inhibitors of repair proteins may have the potential to sensitize selected types of cancer." (PMID 38136273, 2023). "Because of our novel finding that cyclin D1 promotes pyrimidine synthesis, we wondered whether combined inhibition of its main kinase partner (Cdk4) along with the downstream pyrimidine synthesis enzyme dihydroorotate dehydrogenase (DHODH) would synergistically block cancer cell growth." (PMID 38152849, 2023). "Thus, targeted disruption of DHODH can serve as a means for cancer treatment." (PMID 36611901, 2022). "Therefore, extensive efforts have been made to develop DHODH inhibitors for cancer treatment." (PMID 33971967, 2021). "However, it has not yet been fully clarified what exact mechanism of action is responsible for the toxicity of this drug towards cancer cells and whether it is a mechanism dependent on DHODH inhibition." (PMID 34577124, 2021). "Furthermore, this study discovered that the inactivation of DHODH could sensitize GPX4high cancer cells to ferroptosis inducers, and potentiate ferroptosis in GPX4low cancer cells." (PMID 34611144, 2021). "Furthermore, studies suggest the favorable targeting to DHODH in cancer cells living under hypoxia; it is worthwhile to dig into whether DHODH inhibitors with distinct scaffold also exhibit hypoxia-selective anti-cancer activity." (PMID 33971967, 2021). "However, a side product of the pathway, ubiquinol (QH2), is a source of electrons in the electron transport chain, and DHODH also plays a role in alternative (glucose-independent) respiration (utilizing amino acids as an energy source), facilitating cancer development in hypoxic conditions." (PMID 34900699, 2021). "Thus, the effect of DHODH is more predominate in rapidly proliferating cells like cancer cells, which may be highly sensitive to inhibition of nucleotide synthesis." (PMID 33971967, 2021).
cancer (continued). "Consistently with this hypothesis, deletion of DHODH in tumor cells with fully functional OXPHOS suppressed tumor development, while suppression of mitochondrial ATP synthase produced minimal effects, thus implicating DHODH as a potential therapeutic target for OXPHOS-dependent cancers." (PMID 34361078, 2021). "DHODH inactivation could induce extensive mitochondrial lipid peroxidation and ferroptosis in GPX4low-expressing cancer cells, while in GPX4high-expressing cancer cells, these effects could be induced simultaneously by synergistic action with ferroptosis inducers." (PMID 34778060, 2021). "Thus, this suggests that targeting DHODH for cancer therapy is likely to be a safe approach." (PMID 33020720, 2020). "DHODH expression and activity are not linked to an oncogene or tumor suppressor; thus, this enzyme is a nonspecific target, and inhibiting it in cancer patients could cause serious side effects." (PMID 31108873, 2019). "In addition, DHODH is an essential enzyme for the function of normal cells, an observation that raises the question of whether targeting DHODH in cancer patients could be a valid therapeutic opportunity." (PMID 31108873, 2019). "Indeed, β-lapachone, a closely related secondary metabolite of LAP, is a promising drug candidate currently in Phase II clinical trials for the treatment of cancer based on its ability to inhibit DHODH (ClinicalTrials.gov identifier: nCT01502800; ClinicalTrials.gov identifier: nCT02514031)." (PMID 28270195, 2017). "Emerging cancer therapies targeting key enzymes in this pathway, such as CAD and DHODH inhibitors, show potential to disrupt tumor growth." (PMID 40903566, 2026). "In this study, we identify a synthetic lethal interaction between BCOR and DHODH, uncovering a therapeutic vulnerability in BCOR-mutant cells across multiple cancer and cell models." (PMID 41549155, 2026). "Regarding pyrimidine metabolism, the upregulation of CMPK1, CMPK2, CTPS2, CAD, DHODH, and UMPS suggests a role in supporting placental growth under stress, reflecting their established functions in cancer cell proliferation." (PMID 40825832, 2025). "Inhibition of DHODH significantly induced mitochondrial lipid peroxidation and ferroptosis in cancer cells with low GPX4 expression, but only made cancer cells with high GPX4 expression sensitive to ferroptosis." (PMID 41293165, 2025). "Additionally, developing combination strategies that integrate DHODH inhibitors with existing immunotherapies could enhance anticancer efficacy while minimizing adverse effects, potentially leading to more targeted and personalized cancer treatments." (PMID 41144149, 2025). "For instance, low expression of ferroptosis defense genes like FSP1, DHODH, or GPX4 can make cancer cells highly dependent on the remaining defense arm, providing potential targets for inducing ferroptosis in specific cancer types." (PMID 38562143, 2024). "As part of another treatment strategy for cancer metabolism, most research have been concentrated inhibiting enzymes related to UMP synthesis, with a particular focus on drugs targeting DHODH (e.g., leflunomide) and CAD enzymes." (PMID 38704578, 2024). "The most well-studied ferroptosis defence systems in cancers include the GPX4-GSH, FSP1-CoQH2, GCH1-BH4 and DHODH-CoQH2 system." (PMID 38472205, 2024). "In this study, we identified DHODH inhibition as a powerful inducer of antigen presentation and MHC-I expression in diverse cancer cell lines and in HEK-293T cells." (PMID 37066260, 2024). "The expression of DHODH is regulated by the oncogene MYC, which is significantly upregulated in cancer cells and pluripotent cells." (PMID 36814599, 2023).
cancer (continued). "DHODH inhibitors suppress MYC expression, presumably due to the induction of apoptosis and cell cycle arrest in cancer cells." (PMID 36814599, 2023). "Recently, it was proposed a new model for antioxidant enzymes involved in defense against lipid peroxidation in cancer: GPx4 in the cytosol and mitochondria, FSP1 on the plasma membrane, and DHODH in mitochondria." (PMID 35255427, 2022). "Several studies proposed co-targeting DHODH with BRQ and nucleoside uptake via hENT1/2 with dipyridamole in different cancer cell models." (PMID 35203388, 2022). "Inactivation of DHODH in cancer cells with low GPX4 expression significantly increased intracellular lipid peroxidation, while in cancer cells with high GPX4 expression, DHODH inactivation synergized with inducers to enhance ferroptosis." (PMID 36309489, 2022). "CoQ10 can be reduced by different enzymes in cancer cells, for example FSP1 in the plasma membrane and DHODH in the mitochondrial inner membrane." (PMID 35255427, 2022). "In cancer cells, CAD converts glutamate to dihydroorotate, which can be converted to orotate by the mitochondrial enzyme, dihydroorotate dehydrogenase (DHODH) under normoxic conditions." (PMID 34638293, 2021). "Moreover, we showed that blocking nucleoside transport increased the efficacy of DHODH inhibitors in the presence of physiological concentrations of uridine, suggesting a therapeutic strategy to overcome plasma uridine-dependent resistance to DHODH-targeting drugs in cancer patients." (PMID 34462431, 2021). "Additionally, using an mtDNA-depletion model, we found that DHODH-driven pyrimidine biosynthesis is an essential pathway which links respiration to tumorigenesis, demonstrating that DHODH could be a potential wide-spectrum target for cancer therapy." (PMID 33114695, 2020). "Significant differentiation effects were detected for Menin-MLL, DOT1L, and DHODH inhibitors, whereas BET and CDK9 inhibitors primarily induced apoptosis in AML/ALL cancer models." (PMID 31253180, 2019). "DHODH inhibitors could be repurposed as targeted therapies for BCOR-mutant tumors, offering a promising strategy for precision medicine in AML and other cancers." (PMID 41549155, 2026). "Notably, cancer cells exhibit low levels of glutathione peroxidase 4 (GPX4) and inhibition of DHODH hinders respiration, boosts glycolysis and enhances GLUT4 translocation to the plasma membrane." (PMID 38577257, 2023). "Therefore, the examples of DHODH and GPD2 demonstrate the importance of mitochondria-driven biosynthesis in cancer biology along with mitochondria's established bioenergetic, epigenetic, and catabolic roles." (PMID 36632231, 2023). "This could help cancer cells to resist chemotherapy-induced lipid peroxidation and ferroptosis, possibly via the LOXL3/DHODH axis." (PMID 37253718, 2023). "However, in cancer cells with high GPX4 levels, inactivation of DHODH exacerbates mitochondrial lipid peroxidation, in concert with ferroptosis inducers." (PMID 36429080, 2022). "In the cancer cells with low expression of GPX4, DHODH markedly protects cells from ferroptosis." (PMID 35882850, 2022). "Besides, supplementation with the substrate and product of dihydroorotate dehydrogenase (DHODH) attenuated or enhanced the inhibition of ferroptosis induced by GPX4, respectively, especially in cancer cells with low GPX4 expression (GPX4low)." (PMID 34778060, 2021). "A beguiling question is why cancer cells seem to rely mainly on DHODH and not on CAD, which catalyzes half of the reactions in the de novo pyrimidine synthesis pathway." (PMID 31108873, 2019). "Moreover, compared to other cancers, HCC exhibits the highest mRNA expression levels of DHODH." (PMID 40075750, 2025).
cancer (continued). "Thus, it can be reasonably expected that a clinical-grade DHODH inhibitor combined with venetoclax might improve outcomes for HGBCL patients, as well as other cancers with high expression of MYC and BCL2 or MYC and MCL-1." (PMID 38918775, 2024). "Results from this study imply that targeting the FSP1 pathway, but not the DHODH pathway, for sensitizing ferroptosis to kill cancer cells could also impact VKD carboxylation." (PMID 36788244, 2023). "However, research into these defenses is still mostly at the cancer stage, and the specific regulatory mechanisms are not effectively understood, particularly the DHODH pathway, which has not been analyzed in PD and AD research." (PMID 37762411, 2023). "Diverse functions of DHODH uncover its value in multiple diseases not used exclusively for cancer." (PMID 33971967, 2021). "DHODH inhibitors had shown promising in vitro and in vivo activity on solid tumors, but their effectiveness was not confirmed in clinical trials, probably because cancer cells exploited the pyrimidine salvage pathway to survive." (PMID 33670894, 2021). "Leflunomide-mediated growth impairment of cancer cells, however, may not be directly through DHODH inhibition." (PMID 32824193, 2020). "These processes of NOX alteration via DHODH inhibition and the other way round could be important not only in cancer but also during autoimmunity." (PMID 32426367, 2020). "Whereas the newly developed DHODH inhibitor MEDS433 had limited efficacy in vitro when subjected to physiological concentrations of uridine, combining DHODH inhibition and dipyridamole caused an increase in toxicity and, therefore, cell death in AML cells but not in non-cancer cells." (PMID 35203388, 2022). "The combination of DHODH knockdown and GPX4 inactivation, but not either alone, substantially induced mitochondrial lipid peroxidation and ferroptosis in cancer cells, which was reversed by the restoration of GPX4mito but not GPX4cyto98." (PMID 40083691, 2025). "Regrettably, except for DHODH and TXNRD1, the relevance of other candidate genes to human cancer has not been reported." (PMID 36524129, 2022). "Even though this decreasing trend in the amplified transcription of SAMHD1 at 24 h might result in loosening the regulation of CAD, DHODH and UMPS, the critical enzymes involved in direct influx of dTMP (TYMS and TYMP) did not appear to be recovered to normal levels in cancer cells." (PMID 36414668, 2022).